HMOX1 (heme oxygenase 1)
Diseases named in the same sentence as HMOX1 in open-access papers (continued):
Sharing a sentence is not in itself a finding about the gene and the disease.
ischemia (140 papers, 2004 to 2026). A hypoperfusion of the BLOOD through an organ or tissue caused by a PATHOLOGIC CONSTRICTION or obstruction of its BLOOD VESSELS, or an absence of BLOOD CIRCULATION. "TMP also could attenuate the inflammation associated with ischemia by regulating the expression of NF-E2-related factor 2 (Nrf2) and heme oxygenase-1 (HO-1), which plays a role against ischemic reperfusion brain injury." (PMID 27668034, 2016). "Another study showed that TMP reduces the size of infarcts resulting from ischemia/reperfusion injury in vivo, which might be associated with its antioxidant activity via the induction of heme oxygenase-1 (HO-1) and with its capacity for neutrophil inhibition." (PMID 27314011, 2016). "For instance, ginsenoside Rb1 upregulates Nrf2 and heme oxygenase-1 (HO-1) by activating the nuclear factor-related factor 2 (Nrf2)/ARE pathway, which in turn attenuates acute kidney injury caused by intestinal ischemia-reperfusion." (PMID 36814491, 2023). "What’s more, argon significantly upregulate the heme oxygenase-1 (HO-1), a protein protecting neurons against oxidative injury, in both the cortex and hippocampus of the neonatal hypoxia–ischemia brain." (PMID 36532733, 2022). "Heme oxygenase 1 (HO-1) expression can be induced by heme itself, which consequently prevents from harmful effects like oxidative stress, inflammation or ischemia-reperfusion injury." (PMID 33499296, 2021). "The transfer of human HO-1 gene (HMOX1) before myocardial injury provided long-term myocardial protection from ischemia/reperfusion injury." (PMID 31344980, 2019). "Activation of heme oxygenase-1 (HO-1) has been proved to reduce damages to the liver in ischemia reperfusion injury." (PMID 21453462, 2011). "MSCs overexpressed with heme oxygenase-1 (HO-1), an anti-apoptotic and anti-oxidative enzyme, has been shown to remarkably increase transplanted cells survival in ischemia/reperfusion-induced AKI microenvironment and correspondingly contribute to a better renal function." (PMID 36748221, 2024). "Statins may have the potential to reduce oxidative stress by modulating Nrf2-regulated antioxidant genes, such as heme oxygenase 1 (HO-1) known to afford protection in rodent models of ischemia in vivo and in vascular cells in vitro." (PMID 33327440, 2020). "Gene expression ratios of the antioxidant enzymes Gpx1, Sod1 and Sod2, Cat and Hmox1 were evaluated 24 hours after ischemia by means of qRT-PCR to determine whether increased antioxidative capacity might be involved in FXN-mediated neuroprotection." (PMID 29555919, 2018). "Another important gene overexpressed under hypoxia was HMOX1, which is known to have anti-inflammatory effects and may improve survival in the ischemia/reperfusion-acute kidney injury microenvironment." (PMID 27612459, 2016). "The expression of Hmox1, Gclc and Gsta4, all phase II enzymes with Nrf2 related expression, was determined 12 hours after treatment with vehicle, photothrombotic ischemia alone or photothrombotic ischemia and low dose (5 mg/kg) sulforaphane." (PMID 22911746, 2012). "Hmox1 (HO-1, Hsp32) is an extremely sensitive detector of ischemia." (PMID 17653046, 2007). "It is important to note that HMOX1 is a broad-spectrum stress-responsive gene, and its upregulation in peripheral blood can be induced by multiple pathways, including inflammation, oxidative stress, and ischemia, all of which are active in the pathological process of ICH." (PMID 41404462, 2025). "For example, Ginkgo biloba extract can improve cardiac function after global ischemia in the isolated working rat heart by reducing the formation of oxygen free radicals, and sour cherry seed extract can exert cardioprotective effects by increasing heme oxygenase-1 levels." (PMID 31934264, 2019).
ischemia (continued). "Considering that recent studies have revealed the contribution of HSP90 or heme oxygenase-1 to neovascularization, there is a possibility that changes in HSP expression within limb tissue in response to ischemia may in part be associated with the reduced angiogenic potential in the HSF1-KO mice." (PMID 22655083, 2012). "The transcription factor nuclear factor erythroid 2–related factor 2 (Nrf2) plays a key role in mitigating oxidative stress during ischemia by regulating signaling pathways involving Keap1 proteins, PI3K/AKT, MAPK, nuclear factor kappa B (NF-κB), and heme oxygenase-1 (HO-1)." (PMID 41304923, 2025). "Further investigation into the effects of EPA‐induced expression of HMOX‐1 and HMGB1 retention in other systems, including those modeling ischemia reperfusion injury, may reveal other novel protective effects." (PMID 38958135, 2024). "14,15-EET pretreatment could enhance the antioxidant gene expression of glutathione peroxidase (GSH-Px), heme oxygenase-1 (HO-1) and superoxide dismutase (SOD) in cortical neurons after ischemia and reperfusion." (PMID 34575823, 2021). "Another study reports that totarol has vascular protective effects in vivo, by activating the protein kinase B/heme oxygenase-1 (PKB/HO-1) pathway, further increasing superoxide dismutase (SOD) and antioxidant glutathione (GSH) levels, which leads to ischemia-induced brain injury suppression." (PMID 30065158, 2018). "Hassan and Gronert found that PD1 amplified renoprotective heme-oxygenase-1 (HO-1) expression in ischemia-injured and non-injured kidneys, while PD1 inhibited neutrophil infiltration in murine KIR." (PMID 23386851, 2013).
hepatocellular carcinoma (125 papers, 1999 to 2026). A malignant tumor that arises from hepatocytes. "MELK regulated the AKT/mTOR signaling pathway, causing changes in the levels of GPX4, GSH, FTH1, xCT, heme oxygenase 1(HO-1), reactive oxygen species, and Fe2+ to regulate the ferroptosis of hepatoma cells." (PMID 37008632, 2023). "The two drugs synergistically promote HMOX1 expression and subsequently increase the intracellular free iron ion levels, leading to ferroptosis in hepatocellular carcinoma (HCC) cells." (PMID 40959280, 2025). "In hepatocellular carcinoma, the levels of miR-107 are regulated by HMOX1, and their axis participates in the progression of malignancy." (PMID 40671163, 2025). "Polyphyllin I suppressed hepatocellular carcinoma progression by triggering ferroptosis through mitochondrial dysfunction through the Nrf2/HMOX1/GPX4 axis." (PMID 40137309, 2025). "F30, a FGFR4-targeting compound, induces ferroptosis in hepatocellular carcinoma cells by dysregulating iron levels and redox balance, with its effects dependent on HMOX1." (PMID 39315094, 2024). "For example, resistance to sorafenib (a protein kinase inhibitor) in hepatocellular carcinoma was demonstrated to be mediated through HMOX1 regulation of ABC transporters in HCC cells." (PMID 37176114, 2023). "Nrf2 regulates cellular iron and ROS metabolism via p62-Keap1-NRF2 pathway where it protects hepatocellular carcinoma cells against ferroptosis through upregulation of multiple genes (heme oxygenase-1 (HO1) and quinone oxidoreductase-1 (NQO1))." (PMID 34007410, 2021). "It has been reported that miR-15a-3p interacts with HMOX1 to inhibit the metastasis of hepatocellular carcinoma." (PMID 35047556, 2021). "The components of HMOX-1/CO pathway have been shown in hepatocellular carcinoma cells to confer their resistance to TGF-β-mediated growth inhibition by increasing Smad3 phosphorylation via the ERK1/2 pathway." (PMID 32408627, 2020). "Another anti-inflammation and anti-tumor gene, heme oxygenase-1 (HO-1) is induced by Interleukin 6 (IL-6) through the IL-6/Janus kinase (JAK)/STAT3 pathways in hepatoma cells." (PMID 32545625, 2020). "Expression patterns of GCNT3, GDF15, and HMOX1 in Huh7 and L-02 cells after C. pilosula or A. membranaceus treatments were similar to those in hepatocellular carcinoma HepG2 cells." (PMID 30936938, 2019). "The expression patterns of GCNT3, GDF15, and HMOX1 in Huh7 and L-02 cells after treated with qi-tonifying herbs were similar to those in hepatocellular carcinoma HepG2 cells." (PMID 30936938, 2019). "In this study, we examined the role of heme oxygenase-1 (HO-1) in modulating the Cd-induced apoptosis in human hepatoma (HepG2) cells after 24 h exposure." (PMID 26670903, 2015). "The expression of heme oxygenase-1 (HMOX-1) gene was induced by isothiocyanates via NRF2 signaling in HepG2 human hepatoma cells." (PMID 23766854, 2013). "Studies have also shown that HMOX-1 promotes ferroptosis in hepatocellular carcinoma." (PMID 39309491, 2024). "This study indicated that SEH1L siliencing could induce ferroptosis and suppresses hepatocellular carcinoma (HCC) progression via ATF3/HMOX1/GPX4 axis." (PMID 39095556, 2024). "In this study, we obtained that oleanolic acid promotes high expression of HMOX1, PIM1 and ICAM1 in hepatocellular carcinoma cells through oleanolic acid-related expression profiles, which further suggests that HMOX1, PIM1 and ICAM1 are key targets of oleanolic acid." (PMID 38127054, 2023). "However, emerging evidence has revealed HMOX-1 functions as a negative regulator in erastin- and sorafenib-induced hepatocellular carcinoma and knockdown of HMOX-1 by specific shRNA increased erastin- and sorafenib-induced growth inhibition." (PMID 35422048, 2022). "Therefore, HMOX1 is increased in several tumors (hepatoma, pancreatic and prostate cancers, among others) and can increase further in response to chemotherapy and irradiation." (PMID 29560114, 2018).
hepatocellular carcinoma (continued). "SEH1L promotes hepatocellular carcinoma progression by inhibiting ferroptosis, while its silencing induces ferroptosis via the ATF3/HMOX1/GPX4 axis, suppressing tumor growth." (PMID 39315094, 2024). "For example, in hepatocellular carcinoma donafenib and GSK-J4 synergistically induce ferroptosis in tumor cells through upregulation of HMOX1 expression." (PMID 37980165, 2023). "In hepatocellular carcinoma, the degradation of KEAP1 mediated by P62 assists the activation of NAD(P)H quinone dehydrogenase 1 (NQO1), heme oxygenase 1 (HO1), and ferritin heavy chain 1 (FTH1) down-stream of NRF2." (PMID 37152054, 2023). "To investigate resistance to TACE, we downloaded the expression data of EPO, HMOX1, and SERPINE1 in 25 hepatoma cell lines from the CCLE database and used our model to calculate the risk score of each cell line based on this transcriptomic data." (PMID 36213835, 2022). "Specifically, NRF2-mediated induction of the iron-related target genes HMOX-1 and FTH1 protected against ferroptosis; consistently, knockdown of either HMOX-1 or FTH1 by RNA interference enhanced ferroptotic cell death in hepatocellular carcinoma cells." (PMID 28793787, 2018). "Treatment of hepatoma cells (HepG2) with hemin stimulates HO-1 mRNA and protein expression and affects alternative splicing within the 5’ UTR of HMOX1 as well." (PMID 24098580, 2013). "For instance, Momordin Ic can modulate oxidative stress and induce apoptosis in hepatocellular carcinoma cells via the MAPK and PI3K/AKT-mediated mitochondrial pathway, a process dependent on the promotion of heme oxygenase-1 and inducible nitric oxide synthase expression." (PMID 41227351, 2025). "Also, Nrf2-dependent heme oxygenase 1 (HO-1) expression was induced in CYP2E1-overexpressing HepG2 cells, and contributed to ferroptosis resistance in hepatocellular carcinoma cells by modifying iron metabolism and lipid peroxidation." (PMID 36993697, 2023). "Furthermore, in hepatocellular carcinoma cells, knockdown of p62, NQO1, FTH1 and HMOX1 promoted ferroptosis in response to erastin and sorafenib." (PMID 34836129, 2021). "It has been reported that activation of Nrf2 inhibited NAFLD and NASH through upregulating heme oxygenase-1 (HO-1) /NAD(P)H:quinone oxidoreductase 1 (NQO1)/glutathione S-transferase (GST), then promoted hepatocellular carcinoma by competing with Keap1 or through FGFR4–GSK3β signal pathway." (PMID 33114130, 2020).
Hypertension (123 papers, 2008 to 2026). The presence of chronic increased pressure in the systemic arterial system. "For example, promoter polymorphisms resulting in low HMOX1 expression and activity in certain individuals are associated with incident arterial hypertension and with increased mortality." (PMID 38509128, 2024). "Hmox1 encodes for heme oxygenase 1; it is critical for redox balance and is associated with hypertension." (PMID 27462279, 2016). "In accordance with these findings, a previous study reported an association of a polymorphism that also increased HMOX1 expression (−413T/A) in Japanese women with hypertension." (PMID 25933176, 2015). "Either in whole population and in MetS group, we observed a significant association between the HMOX1 S allele and high blood pressure, which remained significant after adjustment for age, gender, and BMI." (PMID 25933176, 2015). "Hmox1 gene encodes for heme oxygenase 1; and it is critical for maintaining NO/oxidative stress balance and is associated with hypertension." (PMID 25517031, 2014). "Ninth, curcumin ameliorated exaggerated vascular contractility by reducing TNF-α and aortic ROS by inducing heme oxygenase-1 (HO-1) in hypertension-associated diabetic rat." (PMID 24348712, 2013). "In addition, our previous studies have shown that pregnant Hmox1-deficient (Hmox1+/−, Het) mice have preeclampsia-like features, such as hypertension and high sFlt 1 levels." (PMID 32784053, 2020). "Therefore, nuclear factor erythroid 2-related factor 2 (Nrf2) signaling as well as its target gene heme oxygenase-1 (HO-1), which is important for antioxidant defense, may also be involved in the progression of hypertension-associated NASH." (PMID 28906458, 2017). "In genes related to “hypertension,” 3 genes were commonly changing in both male DK and HK groups (Il6, Hmox1 downregulated and Ciart upregulated)." (PMID 40232853, 2025). "Several studies have indicated that genetic overexpression or chemical induction of HMOX1 can protect against hypertension, cardiovascular diseases, metabolic conditions, and kidney diseases." (PMID 41262262, 2025). "It has become clear that antioxidant agents such as Tempol and enzymes such as heme oxygenase-1 (HO-1) exhibit a beneficial and protective effect on BP in various animal models of hypertension." (PMID 22518311, 2012). "Apart from the GT-repeat, previous studies implied a potential influence of the AA-genotype of SNP rs2071746 (g.4613A>T) located in the 5′-region of HMOX1 in hypertension and coronary artery disease." (PMID 22666428, 2012). "Angiotensin II (AngII) causes hypertension (HTN) and promotes renal injury while simultaneously inducing reno-protective enzymes like heme oxygenase-1 (HO-1)." (PMID 22506099, 2012). "Hypertension may induce liver injury and hepatic fibrosis through decreased interleukin-10-mediated or heme oxygenase-1-induced anti-inflammatory mechanisms." (PMID 37749307, 2023). "Additionally, increased cardiac heme oxygenase-1 (HO-1) activity associated with N. sativa reduces angiotensin II-induced inflammation and NADPH oxidase-mediated oxidative stress, which collectively contribute to the attenuation of hypertension in this model." (PMID 40338252, 2025). "Likewise, genetic deletion of heme oxygenase-1 (HO-1) caused induction of NOX-2 at the protein level, increased levels of vascular ROS, and endothelial dysfunction, all of which were further aggravated by AT-II-induced hypertension." (PMID 31341533, 2019). "Hypertension may induce liver regeneration and fibrosis through an endothelial dysfunction due to increased angiocrine signals and may also be triggered by glucose intolerance and decreased interleukin-10-mediated or heme oxygenase-1-induced anti-inflammatory mechanisms." (PMID 35268536, 2022).
Hypertension (continued). "In the RNA-Seq dataset, the identification of four DEGs related to regulation of BP, namely Guca2b, Hmox1, Hba2, and Hba-a2, is of particular interest for elucidating possible mechanisms by which l-NAME and/or l-citrulline medicates programmed hypertension." (PMID 25517031, 2014). "Importantly, Hmox1−/− mice displayed upregulated NOX2 protein expression, vascular oxidative stress, markers of inflammation, endothelial dysfunction, and hypertension in response to angiotensin-II." (PMID 33921821, 2021). "In fact, it has been shown that the induction of HMOX1, through the generation of bilirubin, favors vessel relaxation by acting on the transport of calcium and potassium, and thereby improving EDH in a rat model of spontaneous hypertension." (PMID 32082188, 2020). "However, the direct link between hypertension, ROS, and IA development is not obvious, as heme oxygenase-1 expression is downregulated in patients with hypertension." (PMID 34743248, 2022). "Since hypertension is a complex disease, the impact of HMOX1 (GT)n on hypertension may not be straightforward but could be modulated by environmental and other genetic factors." (PMID 25933176, 2015).